MMP9 (matrix metallopeptidase 9)
Diseases named in the same sentence as MMP9 in open-access papers (continued):
Sharing a sentence is not in itself a finding about the gene and the disease.
silicosis (7 papers, 2015 to 2025). Silicosis is a respiratory disease caused by breathing in (inhaling) silica dust. "In silicosis, MMP9 and TIMP1, its endogenous inhibitors are disrupted to accelerate abnormal deposition of the Extracellular Matrix (ECM)." (PMID 40470053, 2025). "A previous study analyzing the plasma levels of TNF-α and MMP-9 in patients with silicosis has suggested that both molecules have higher expression in the early course of silica exposure." (PMID 29126438, 2017). "Also, SiO2 induced macrophage senescence and silicosis in lung tissue, both of which were accompanied by increased fibrosis-associated factors (IL-1β, IL-6, TNF, and TGF-β1) and MMPs (MMP2, MMP9 and MMP12)." (PMID 35959439, 2022). "In conclusion, we identified TNF, MMP9, NF-κB1 and TLR2, that contribute to the therapeutic effects of PFD in silicosis." (PMID 40470053, 2025). "As MMPs play important roles in the pathogenesis of silicosis, we examined the expression of MMP2 and MMP9 in silica-treated MLE-12 cells." (PMID 26340635, 2015). "Network pharmacology identifies TNF, MMP9, and NF-κB1 as key genes in PFD’s anti-silicosis effect." (PMID 40470053, 2025). "We found that PFD may alleviate inflammation and fibrosis in silicosis by inhibiting the TLR2/NF-κB pathway in epithelial cells, thereby reducing the production of TNF and MMP9." (PMID 40470053, 2025). "Compared with healthy controls, silicosis patients had remarkably higher plasma concentrations of matrix metalloproteinase-2 (MMP-2), matrix metalloproteinase-9 (MMP-9), collagen alpha-1(I) protein (COL1A1), and collagen alpha-1(III) protein (COL3A1) (all p < 0.05)." (PMID 30558126, 2018).
status epilepticus (7 papers, 2012 to 2025). Status epilepticus is defined as a continuous seizure lasting more than 30 min, or two or more seizures without full recovery of consciousness between any of them. "In their study the administration of pilocarpine initiated status epilepticus in rats what was associated with overexpression of MMP-9 and a decrease of β1-integrin concentration and consequently with death of hippocampal cells in the mechanism of apoptosis." (PMID 28104930, 2016). "Overall, status epilepticus-induced dendritic spine loss in the ML of the DG appears to be mediated by MMP-9 release from spines in response to seizures." (PMID 25071472, 2014). "MMP-9 levels increase after acute brain injuries including status epilepticus, and are linked to increases in permeability of the BBB." (PMID 22507553, 2012). "It has been shown that inhibitors of MMP-9 used in status epilepticus animal model, reduced neuronal cell death, modified the inflammatory response by suppression of pro-inflammatory cytokines in microglial cells." (PMID 31172215, 2019). "MMP-9 is also induced during status epilepticus after treatment with kainate and pilocarpine." (PMID 25071472, 2014). "Experimental studies have shown that the HMGB1 monoclonal antibody can suppress MMP-9 expression and prevent BBB leakage in animal models of status epilepticus." (PMID 40806813, 2025).
Telangiectasia (7 papers, 2022 to 2025). Telangiectasias refer to small dilated blood vessels located near the surface of the skin or mucous membranes, measuring between 0.5 and 1 millimeter in diameter. "Lactobionic acid can be chelating agent with matrix metalloproteinase (such as MMP9), to reduce skin laxity and telangiectasia." (PMID 40111222, 2025). "It improves clinical signs such as lid margin telangiectasia, MG functionality, and tear MMP-9 expression levels, as well as relieving subjective symptoms." (PMID 36012963, 2022). "This was especially true for the lid margin telangiectasia and ocular surface MMP-9 expression levels." (PMID 36012963, 2022).
uveal melanoma (7 papers, 2017 to 2022). A melanoma derived from melanocytes of the uveal tract. "We correlate these observations to the increased levels of active metalloproteinase MMP9 indicating a reciprocal cellular interaction between retinal pericytes and uveal melanoma that induces effective cellular responses also in the tumor." (PMID 32756477, 2020). "Activated pericytes triggered the increase of uveal melanoma invasiveness through the upregulation of the active MMP9 isoform." (PMID 32756477, 2020). "Previous studies have reported that the PI3K/AKT/MMP-9 pathway is a unique downstream pathway of HMGA1, which is critical for uveal melanoma cell proliferation, survival, and migration." (PMID 36479041, 2022). "Similarly, in uveal melanoma, this miRNA led to elevated cell proliferation and migration in a PI3K/AKT MMP9 (matrix metalloproteinase 9)-dependent manner." (PMID 33430277, 2021).
vascular dementia (7 papers, 2010 to 2025). A degenerative vascular disorder affecting the brain. "These immune-related pathways, including IL-17 signaling (p = 0.027874) and TNF signaling (p = 0.033137), both involving MMP9, demonstrated the role of neuroinflammation in the development of vascular dementia." (PMID 41032496, 2025). "The enrichment of nuclear receptor signaling (APOE and MMP9) links lipid metabolism, inflammation, and endothelial function, confirming the multidimensional nature of the etiology of vascular dementia." (PMID 41032496, 2025). "A third study found lower MMP-9 concentrations in CSF of individuals with AD or vascular dementia (VaD) with lobar CMBs (n = 32) compared with AD or VaD patients without lobar CMBs (n = 27) and cognitively normal controls (n = 26)." (PMID 30483207, 2018). "Intriguingly, patients with vascular dementia have been noted to have higher levels of MMP-9 in CSF even compared to patients suffering from AD." (PMID 26538832, 2015). "The chosen proteins Apolipoprotein E (APOE), Amyloid Beta Precursor-Like Protein (APLP), Claudin-5 (CLDN5), Superoxide Dismutase (SOD), Matrix Metalloproteinase-9 (MMP-9), and Methylenetetrahydrofolate Reductase (MTHFR) play a key role in the progression of vascular dementia." (PMID 41032496, 2025). "MMP activity studies using gelatin zymography have shown MMP-9 activity to be elevated in CSF of patients with vascular dementia, but not in patients with AD, when compared to controls." (PMID 36717932, 2023).
blepharitis (6 papers, 2022 to 2024). Inflammation of the eyelids near the eyelashes. "Matrix metallopeptidase 9 (MMP-9) concentration is also elevated in blepharitis and other ocular surface diseases." (PMID 37104297, 2023). "However, analyzing the iPD groups separately, we see that there is stronger MMP-9 overexpression in iPD patients with blepharitis, 3.08 times that in iPD patients without blepharitis." (PMID 35076620, 2022).
bronchopulmonary dysplasia (6 papers, 2011 to 2026). Bronchopulmonary dysplasia is a chronic respiratory disease that results from complications related to lung injury during the treatment of infant acute respiratory distress syndrome in low-birth-weight premature infants or from abnormal lung development in older infants. "Experimental studies have shown that in a rat model of LPS-induced bronchopulmonary dysplasia (BPD), the massively formed NETs cleave fibronectin via NE and MMP-9 to further degrade ECM in the alveoli, thereby promoting the development of BPD." (PMID 34327245, 2021). "Increased activity of matrix metalloproteinase-9 (MMP-9) likely plays a role in fetal lung injury, because elevated cord blood MMP-9 has been correlated with bronchopulmonary dysplasia severity and oxygen supplementation." (PMID 22216148, 2011). "There is a significant lack of data regarding MMP‐9 expression in normal human fetal lungs; moreover, most existing studies focus on pathological conditions such as bronchopulmonary dysplasia and pulmonary hypoplasia." (PMID 40952045, 2026).
cardiac arrest (6 papers, 2014 to 2026). Cessation of breathing and/or cardiac function. "Employing a pig model of cardiac arrest following left anterior descending coronary artery ischemia, we showed a significantly increased enzymatic activity of MMP-9 in the ischemic myocardial tissue." (PMID 24712447, 2014). "Out-of-hospital cardiac arrest (OHCA) leads to an inflammatory response, including alterations in matrix metalloproteinase (MMP)-9 and tissue inhibitor of matrix metalloproteinase (TIMP)-1 concentrations." (PMID 41503448, 2026). "To extend the knowledge on the temporal evolution of MMP-9 and TIMP-1 concentrations after cardiac arrest, we analysed MMP-9 and TIMP-1 concentrations from admission and compared the levels between OHCA patients and patients with cardiovascular disease burden without cardiac arrest." (PMID 41503448, 2026). "Furthermore, NaHS exhibited neuroprotective properties in cardiac arrest models by reducing brain edema and BBB disruption through inhibition of matrix metalloproteinase-9 (MMP-9) expression and stabilization of occludin." (PMID 41465271, 2025). "Our results are consistent with previous data showing that MMP-2 (more than MMP-9) plays a critical role in BBB disruption, glial cell activation, and white matter damages after chronic cerebral hypoperfusion in animal models and patients with cardiac arrest." (PMID 36010557, 2022). "After out-of-hospital cardiac arrest (OHCA), blood concentrations of matrix metalloproteinase (MMP)-9 are increased, but their role has not been properly investigated." (PMID 41503448, 2026).
chronic bronchitis (6 papers, 2009 to 2025). A type of chronic obstructive pulmonary disease characterized by chronic inflammation in the bronchial tree that results in edema, mucus production, obstruction, and reduced airflow to and from the lung alveoli. "Several MMPs including MMP-8, MMP-9 and MMP-12 have been associated with COPD; in our recent study only the levels of MMP-8 were higher in chronic bronchitis compared to asymptomatic smokers." (PMID 19473482, 2009).
colon adenocarcinoma (6 papers, 2013 to 2024). "Whereas colonic adenocarcinoma strongly expressed MMP-9, two benign breast lesions (fibroadenoma and myofibroblastoma) failed entirely to express MMP-9 under the same conditions." (PMID 25151367, 2014). "ZNF692 promotes cell proliferation, migration, and invasion in colon adenocarcinoma (COAD) by downregulating p27kip1 or upregulating cyclin D1, cyclin-dependent kinase 2 (CDK2), matrix metalloproteinase-9 (MMP-9), and PI3K/Akt signaling." (PMID 36358661, 2022).
complication (6 papers, 2015 to 2025). Any disease or disorder that occurs during the course of, or because of, another disease, treatment, or procedure. "Genetic variances on MMP-9 gene are demonstrated to be associated with the risk of developing diabetic microvascular complications." (PMID 26692905, 2015). "Levels of HbA1c, LDL, triglycerides, MMP-1, MMP-2, MMP-3, MMP-9, MMP-10, TIMP-1 and markers of LGI and ED were significantly higher in individuals with vascular complications compared to those without." (PMID 25848912, 2015).
corneal ulcer (6 papers, 2009 to 2024). Area of epithelial tissue loss from corneal surface; associated with inflammatory cells in the cornea and anterior chamber. "MMP2, MMP3, and MMP9 have been previously reported to be upregulated in inflammatory/fibrotic diseases of the ocular surface, such as corneal ulcer, ocular burn, and corneal neovascularization." (PMID 35943663, 2022). "In the present study, the activity of gelatinases (MMP-2 and MMP-9) was significantly high in the corneal ulcer control positive group, which significantly decreased after treatment with autologous PRP in both dogs and cats." (PMID 33816586, 2021). "The activity percentages of both MMPs (MMP-2 and MMP-9) were significantly high in the corneal ulcer control positive group (diseased group), which significantly decreased (p ≤ 0.05) after treatment with autologous PRP treated groups in both animals." (PMID 33816586, 2021). "Angiogenesis complicating fungal keratitis likely results from production of VEGF-A and other mediators such as MMP-9 that increase during corneal infection and inflammation." (PMID 19816603, 2009). "Also, in co-bacterial and fungal infections of human cornea, it was reported that the gene MMP9 (Matrix metalloproteinase 9) was observed to have differential expression in late stages of corneal ulcer tissue." (PMID 39204419, 2024).
coronary artery stenosis (6 papers, 2013 to 2025). "Genetic variants with documented pharmacologic or disease associations may influence ACS susceptibility, and an association between MMP-9 polymorphisms and coronary artery stenosis has previously been reported in the Uyghur population." (PMID 40894214, 2025). "Plasma NGAL levels were positively related with MMP-9 and IL-1β levels and severity of coronary stenosis." (PMID 31387110, 2019). "Elevated MMP-9 plasma levels in the peripheral blood have been detected in the patients with ACS and are associated with severe coronary stenosis and cardiovascular mortality." (PMID 23737852, 2013). "NGAL had a better ability to discriminate severe coronary stenosis than MMP-9, IL-1β, and hs-CRP." (PMID 31387110, 2019). "NGAL had a better ability to discriminate severe coronary stenosis than MMP-9, IL-1β, or hs-CRP." (PMID 31387110, 2019). "Currently, degree of coronary arterial stenosis has been positively correlated with MMP-9." (PMID 26150861, 2015). "Spearman’s correlation coefficient analysis found a positive correlation between the levels of MMP-9, PAF, and the degree of coronary artery stenosis and plaque severity (P<0.05)." (PMID 40821655, 2025). "On the other hand, we also found a significant correlation between MMP-9 and PAF and ACS patients with coronary stenosis and plaque severity, which again validates the important link between the two chicken ACS." (PMID 40821655, 2025). "There was a positive correlation between MMP-9, PAF and the degree of coronary stenosis and plaque severity (P<0,05)." (PMID 40821655, 2025).
diabetic macular edema (6 papers, 2016 to 2025). "MMP-2 and MMP-9 are also implicated in the pathogenesis of diabetic macular edema and fibrovascular proliferation with tractional retinal detachment, which are the most common causes of vision loss in patients with DR." (PMID 32403389, 2020). "MMP-9, which is upregulated in DR, cleaves Netrin-1 into a bioactive VI-V fragment that increases vascular permeability and diabetic macular edema, and inhibiting MMP-9 prevents this pathological permeability." (PMID 41196411, 2025). "We hypothesize that MMP-1 and MMP-9 have major roles in the initiation of inner BRB damage and in the induction of diabetic macular edema (DME)." (PMID 27467659, 2016). "Patients with diabetic macular edema are characterized by higher levels of MMP-1 and MMP-9 in the aqueous humor compared to patients without, suggesting that these two enzymes promote the prevalence of diabetic macular edema." (PMID 35457074, 2022). "In the AH of diabetic macular edema patients, MMP-1 and MMP-9 concentrations are higher than normal." (PMID 32596291, 2020). "It is not excluded that local intraocular injection of neutralizing antibodies against MMP-9 may be helpful in diabetic macular edema and even replace anti-VEGF agents in those patients with diabetic macular edema, who do not respond to anti-VEGF therapy." (PMID 36164340, 2022).
E. coli infection (6 papers, 2018 to 2025). "E. coli infection resulted in the upregulation of the genes encoding proteases, which participate in the degradation of ECM, namely, ADAM10 (logFC of 2.62), ADAM17 (logFC of 8.75), MMP9 and MMP14 (both with a logFC of 2.58), CAPN7 and CAST (both with logFC of 2.20)." (PMID 32234079, 2020). "To better understand differences in PICD between neonatal and adult monocytes we here study the regulation of MMP-9 and TACE expression in CBMO and PBMO after E. coli infection." (PMID 30897723, 2019). "The present study compared the induction of PICD in infected and non-infected monocytes (bystander cell death) from cord blood and adult blood, utilizing an in vitro E. coli infection model with respect to a distinct regulation pattern of the metalloproteinases TACE and MMP-9." (PMID 30897723, 2019). "In both PBMO and CBMO, E. coli infection increased the portion of MMP-9-expressing cells but did not have an effect on MMP-2 protein expression." (PMID 30524196, 2018).
exfoliation glaucoma (6 papers, 2010 to 2025). "For example, MMP-2 and MMP-9 levels were reduced in pseudoexfoliation glaucoma, while MMP-9 activity in tears was increased in primary open-angle and angle closure glaucoma." (PMID 31398819, 2019). "In the Russian population, the variant G allele of rs2250889 MMP9 (which was also analysed in our study) was significantly associated with a higher risk of POAG and exfoliative glaucoma, while the rs3918249 MMP9 C allele decreased the risk of exfoliative glaucoma." (PMID 39769228, 2024). "Although other authors have described using the MMP-9 test in patients after refractive surgery procedures with DED and pseudoexfoliation syndrome, our study allowed the effects of chronic glaucoma treatment on proinflammatory biomarkers to be examined." (PMID 31073413, 2019).
Fibroadenoma (6 papers, 2014 to 2026). A benign tumor of the breast characterized by the presence of stromal and epithelial elements. "Few studies have evaluated the immunohistochemical expression of MMP-2 and MMP-9 in BC and fibroadenoma." (PMID 34445715, 2021). "Some authors have found significantly higher MMP-2 and MMP-9 protein expression in BC cells than in fibroadenoma." (PMID 34445715, 2021). "In addition, the levels of VEGF and MMP-9 were significantly higher in IDC patients than in the fibroadenoma patients and healthy adults, and the level of MMP-9 exhibited a positive correlation with the level of VEGF." (PMID 24944618, 2014). "In the present study, the levels of VEGF and MMP-9 were compared among IDC patients, fibroadenoma patients and healthy adults." (PMID 24944618, 2014).
focal segmental glomerulosclerosis (6 papers, 2014 to 2022). A renal disorder characterized by sclerotic lesions in the glomeruli. "Abnormal expression of MMP-9 is involved in proteinuria-related kidney diseases, including focal segmental glomerulosclerosis and anti-glomerular basement membrane inflammation." (PMID 35439732, 2022). "Typical patterns of MMP-2 and MMP-9 are differentially expressed in patients with focal segmental glomerulosclerosis, minimal change disease, membranous nephropathy, and ANCA-associated vasculitis." (PMID 31963569, 2020). "Furthermore, it has been reported that MMP2 and MMP9 are differentially expressed in patients with minimal change disease, focal segmental glomerulosclerosis and membranous nephropathy." (PMID 35045102, 2022). "MMP-9/NGAL ratio is considered an important marker of the differentiation of minimal change disease and focal segmental glomerulosclerosis in children with nephrotic syndrome." (PMID 24719498, 2014).
gastroesophageal junction adenocarcinoma (6 papers, 2017 to 2022). A carcinoma that arises from glandular epithelial cells of the esophagogastric junction. "An example is the use of nivolumab combined with andecaliximab (GS-5745), an inhibitory mAb of matrix metalloproteinase 9 (MMP-9) in recurrent gastric or gastroesophageal junction adenocarcinomas (NCT02864381)." (PMID 29312320, 2017). "Thus, MMP9 remains an attractive therapeutic target for gastric or GEJ adenocarcinoma." (PMID 35773363, 2022). "In addition, andecaliximab, an anti-MMP-9 antibody along with standard chemotherapies such as oxaliplatin, cisplatin and mFOLFOX6 resulted in reduced angiogenic activity in the TME and further improved outcome in patients with gastric and gastroesophageal junction adenocarcinoma." (PMID 33276524, 2020).
hepatic (6 papers, 2015 to 2024). "Therefore, MMP-9 could play an important role in the degradation of extracellular matrix and also by releasing some factors, e.g., soluble Kit-ligand, leading to enhanced differentiation and proliferation capacity of transplanted BM-MSCs in liver inflammation induced by CCl4." (PMID 33564610, 2021).